MMP7 (matrix metallopeptidase 7)
Diseases named in the same sentence as MMP7 in open-access papers (continued):
Sharing a sentence is not in itself a finding about the gene and the disease.
chondrosarcoma (7 papers, 2015 to 2025). A malignant cartilaginous matrix-producing mesenchymal neoplasm arising from the bone and soft tissue. "Our previous study investigated the suppressive effects of ugonin V on chondrosarcoma metastasis by targeting MMP7 expression." (PMID 39897041, 2025). "Melatonin inhibits chondrosarcoma cell proliferation by inhibiting matrix metalloproteinase 7 (MMP7)." (PMID 40756978, 2025). "In chondrosarcoma cells, it has been demonstrated that increased shear stress via cAMP elevation induced MMP7 expression." (PMID 30621194, 2019). "We next sought to decipher the critical transcription factor(s) responsible for MMP-7 synthesis in sheared chondrosarcoma cells." (PMID 25823818, 2015). "Because fluid shear induces MMP-9 synthesis in human chondrocytes via PI3-K- and MAPK-dependent pathways, we evaluated the potential role of these signaling pathways in MMP-7 upregulation in shear-activated chondrosarcoma cells." (PMID 25823818, 2015). "Specifically, fluid shear stress induces the synthesis of cAMP and IL-1β, which in turn activate PI3-K-, ERK1/2-, p38-dependent signaling pathways leading to MMP-7 induction via transactivation of NF-κB and c-Jun in human chondrosarcoma cells." (PMID 25823818, 2015). "In agreement with these prior reports, our data reveal that shear stress exposure increases the lung colonization of human chondrosarcoma cells via MMP-7 activation." (PMID 25823818, 2015). "Specifically, shear-induced cAMP and IL-1β activate PI3-K, ERK1/2 and p38 signaling pathways, which lead to the synthesis of MMP-7 via transactivating NF-κB and c-Jun in human chondrosarcoma cells." (PMID 25823818, 2015). "MMP-7 is tightly regulated under physiological conditions and is elevated during the course of chondrosarcoma mesenchymal transformation." (PMID 25823818, 2015). "Consistent with prior findings, MMP-7 immunostaining was markedly elevated (~3-fold) in human chondrosarcoma tissues relative to normal bone controls." (PMID 25823818, 2015). "Shear-induced MMP-7 potentiates chondrosarcoma cell motility and invasion, leading to the enhanced lung colonization of chondrosarcoma cells in vivo." (PMID 25823818, 2015). "We next aimed to delineate the signaling cascade of MMP-7 induction in shear-activated chondrosarcoma cells." (PMID 25823818, 2015). "In summary, we have elucidated the signaling pathway by which fluid shear stress upregulates the expression of MMP-7 in human chondrosarcoma cells." (PMID 25823818, 2015). "In view of these findings and given that fluid shear is a relevant biomechanical signal in bone and cartilage (patho)physiology, we herein delineated the signaling pathways of MMP-7 induction in shear stress-activated human chondrosarcoma cells." (PMID 25823818, 2015). "In light of these findings, we also assessed the potential contribution of MMP-7 to the migration and invasion of human chondrosarcoma cells." (PMID 25823818, 2015). "Prior work has suggested that MMP-7 correlates with the degree of malignancy in human chondrosarcoma." (PMID 25823818, 2015). "Apart from cAMP, IL-1β has a critical role in inducing the expression of MMP-7 in shear-activated human chondrosarcoma cells." (PMID 25823818, 2015). "MMP-7 expression correlates with the degree of malignancy in chondrosarcoma." (PMID 25823818, 2015). "Collectively, our data suggest that fluid shear induces the accumulation of both cAMP and IL-1β, which in turn activate the AKT, ERK1/2 and p38 signaling pathways that are responsible for the elevated MMP-7 expression and enzymatic activity in himan chondrosarcoma cells." (PMID 25823818, 2015). "In addition, activation of PI3-K/AKT, ERK1/2, and p38 pathways leads to synthesis of MMP-7 in human SW1353 chondrosarcoma cells." (PMID 25823818, 2015). "Therefore, both cAMP and IL-1β are key signaling molecules in mediating shear-induced MMP-7 expression in human chondrosarcoma cells." (PMID 25823818, 2015).
chondrosarcoma (continued). "We further demonstrate the contribution of MMP-7 activation to lung colonization in vivo which may help us gain insights into therapeutic strategies aiming to combat chondrosarcoma metastasis." (PMID 25823818, 2015). "Importantly, MMP-7 upregulation in response to shear stress exposure has the ability to promote lung colonization of chondrosarcomas in vivo." (PMID 25823818, 2015). "Although MMP-7 is elevated in advanced stages of chondrosarcoma disease as well as in shear-activated chondrosarcoma cells, the signaling mechanism by which MMP-7 activation may contribute to chondrosarcoma invasion and metastasis has yet to be investigated." (PMID 25823818, 2015). "Moreover, we report the critical roles of shear stress in promoting chondrosarcoma lung colonization in mice via the induction of the enzymatic activity of MMP-7." (PMID 25823818, 2015). "We herein demonstrate the pivotal role of endogenous cAMP in fluid shear stress-induced MMP-7 synthesis, which was substantiated by the use of adenylate cyclase inhibitor SQ22536 that essentially abrogated MMP-7 induction in shear-activated chondrosarcoma cells." (PMID 25823818, 2015). "MMP-7 expression is also upregulated in shear-activated chondrosarcoma cells." (PMID 25823818, 2015). "However, the mechanism of MMP-7 regulation and its biological functions in chondrosarcoma metastasis in vivo remain unclear." (PMID 25823818, 2015). "Interestingly, the adenylate cyclase inhibitor SQ22536 or an anti-IL-1β antibody alone were effective in suppressing the shear-induced upregulation of AKT, ERK1/2 and p38 phosphorylation, which result in MMP-7 suppression in shear-activated SW1353 chondrosarcoma cells." (PMID 25823818, 2015). "MMP-7 may thus serve as a useful indicator in the diagnosis of chondrosarcoma." (PMID 25823818, 2015). "PI3-K, ERK1/2 and p38 transactivate the phosphorylation of c-Jun and NF-κB, which in turn bind to the MMP-7 promoter and mediate MMP-7 mRNA and protein synthesis in human shear-stimulated chondrosarcoma cells." (PMID 25823818, 2015). "Moreover, MMP-1, MMP-7 and MMP-9 expression was found to be highest in the invasive protrusions of chondrosarcomas." (PMID 29361725, 2018). "MMP-1, MMP-2, MMP-3, MMP-7, MMP-9 and MMP-13 are frequently expressed in chondrosarcoma tissues." (PMID 29361725, 2018). "Some individual chondrosarcomas also exhibited elevated levels of MMP-1, MMP-7 and MMP-9 mRNAs." (PMID 29316907, 2018). "Prior work revealed that MMP-7 is detected in human chondrosarcoma but not normal cartilage." (PMID 25823818, 2015). "ERK1/2 activation could provide a source for upregulation of MMP-7 expression in human chondrosarcoma cells, but ERK1/2 activation may not be sufficient to achieve full activity of MMP-7." (PMID 25823818, 2015).
colorectal tumors (7 papers, 2003 to 2024). "Colorectal tumor progression was associated with overexpression of MMP-7 and MMP-14, which is also known as a membrane type 1-matrix metalloproteinase (MT1-MMP)." (PMID 28272349, 2017). "On the other hand, MMP-2 and MMP-7 expression levels in the colorectal tumors were further increased by OPN deficiency." (PMID 28505114, 2017). "In addition, the association between MMP7 and invasive development of tumors as well as distant metastasis has been observed in colorectal tumors (CRC)." (PMID 38097858, 2024). "Besides, impaired overall survival appears in patients with colorectal tumors expressing high levels of MMP7." (PMID 27431388, 2016). "Correlation among expression of p-c-Jun, TCF, β-Catenin and MMP7 in all colorectal tumors (n = 68)." (PMID 18992165, 2008). "MMP-3, MMP-9, MMP-13, MMP-2, and MMP-7 were upregulated in colorectal tumors in Min/OPN(+/+) compared to adjacent non-tumor parts." (PMID 28505114, 2017). "On the other hand, elevated expressions of MMP-2 and MMP-7 in colorectal tumors in Min mice were not lowered but rather increased by OPN deficiency in the present study." (PMID 28505114, 2017). "Additionally, a high percentage of human colorectal tumours expressed both MMP-7 and COX-2, although, the levels and localisation of MMP-7 and COX-2 expression within the tumours did not correlate." (PMID 12778076, 2003).
diabetic kidney disease (7 papers, 2014 to 2025). Progressive kidney disorder caused by vascular damage to the glomerular capillaries, in patients with diabetes mellitus. "In a clinical trial setting, canagliflozin treatment in individuals with diabetic kidney disease decreased the levels of inflammation and fibrosis biomarkers, including IL-6, matrix metallopeptidase 7 (MMP7) and fibronectin 1(FN1)." (PMID 34680522, 2021). "Similar results are reported in kidney with MMP-7 activity and protein expression reduced under conditions of diabetic nephropathy." (PMID 25853140, 2015). "In addition, a decrease in serum MMP7 levels has also been shown following treatment of diabetic kidney disease with a sodium–glucose cotransporter 2 inhibitor, likely reflecting an improvement in extracellular matrix turnover and fibrosis." (PMID 33536476, 2021). "In addition, SGLT2is have been shown to reduce circulating levels of interleukin 6 (IL-6), tumor necrosis factor 1 (TNF-1) receptor, and matrix metalloproteinase-7 (MMP-7) and fibronectin-1, key molecules in the formation process of diabetic kidney disease." (PMID 41007686, 2025). "Multiple studies have demonstrated that CKD patients, including those with diabetic kidney disease (DKD) and IgAN, have significantly higher MMP-7 levels in blood and urine compared to healthy individuals, and that urinary MMP-7 is an independent predictor of IgAN progression and correlates with RF." (PMID 40809416, 2025).
gastric tumor (7 papers, 2010 to 2024). "Among the 285 gastric tumour tissues examined, the incidence of positive MMP-7 expression was 34.4% (98/285)." (PMID 33005257, 2020). "Gastric tumour tissues were stained immunohistochemically to evaluate expression of MMP-7 and TIMP-1." (PMID 33005257, 2020). "The MMP7 positive expression rate was 45–48.5% in four studies using IHC, and 66.7% in one using rt-PCR to detect MMP7 in different parts of gastric tumor specimens; IHC-positive staining was up to 74.1% in the study assessing tumor invasive front." (PMID 25919283, 2014). "To investigate whether in vitro expression correlated with expression in vivo, we analyzed the mRNA expression of MMP-7 in gastric tumor samples that exhibited upregulated HSP47." (PMID 38907287, 2024). "In conclusion, coexpression of MMP-7 and its inhibitor TIMP-1 in gastric tumour tissues is a potential prognostic marker for GC." (PMID 33005257, 2020). "Downregulated miR-148a expression was found in gastric tumor compared with non-neoplastic mucosa, and this was correlated with advanced tumor invasiveness and poor prognosis by targeting MMP7." (PMID 28574848, 2017).
heart failure (7 papers, 2019 to 2025). Inability of the heart to pump blood at an adequate rate to meet tissue metabolic requirements. "Several biomarkers—including IGFBP-1, IGFBP-2, IGFBP-3, FGF-23, MMP-2, MMP-7, TIMP-2, and RAGE/AGE—were significantly elevated in patients with cardiac involvement and independently associated with either heart failure decompensation or death/transplantation." (PMID 41226753, 2025). "Our results showed higher expression of MMP-2, 7 and 9, the key gelatinases involved in ECM degradation in AFib patients corroborating previous findings on human samples, while elevated MMP-7 was seen in rats with mild and severe heart failure." (PMID 31822289, 2019). "Addition of GDF15, PARC, and MMP7 increased the C-statistic for heart failure from 0.59 to 0.70." (PMID 39695064, 2025). "Further evidence about the interplay between the heart and the kidney stems from biomarker studies demonstrating that biomarkers of kidney disease progression, such as the ones identified in our study, TNFR-1, KIM-1, IL-6, MMP-7, also predict the composite heart failure outcome." (PMID 36151557, 2022). "Nevertheless, the utility of MMP-7 as a potential biomarker may also be related to its role in other medical conditions, such as heart failure as well as oncological diseases." (PMID 32101136, 2020). "Five biomarkers, GDF15, IL6, MMP1, MMP7, and TNFR2, were significantly associated with all 6 non-cancer aging-related conditions, mortality, mobility limitation, heart failure, coronary heart disease, stroke, and dementia." (PMID 39695064, 2025).
lung adenocarcinoma (7 papers, 2012 to 2025). A carcinoma that arises from the lung and is characterized by the presence of malignant glandular epithelial cells. "We observed a remarkable upregulation of the ADAM, EGF, and MMP-7 protein levels in lung adenocarcinoma, while after the SH intervention, these conditions were significantly reversed." (PMID 41444284, 2025). "In addition, the expression of COX-2 can regulate matrix metalloproteinases (MMP-7), leading to proliferation and invasion of lung adenocarcinoma." (PMID 36384712, 2022). "NCI-H441 human lung adenocarcinoma cells with forced Ascl1 expression and BEAS-2B human immortalized bronchial cells overexpressing MMP-7 were treated with the alkylating anti-cancer drug cisplatin and non-alkylating anti-cancer drugs etoposide and docetaxel." (PMID 23300791, 2012). "The investigators suggested that the concentrations of MMP7 and MMP9 and the circulating tumor cell count could be used together as an effective, clinically predictive panel for lung adenocarcinoma metastasis and prognosis." (PMID 31191742, 2019). "To investigate if MMP-7 and MGMT are downstream genes of Ascl1, we overexpressed Ascl1 in human lung adenocarcinoma cells H441 which are normally negative for Ascl1 expression." (PMID 23300791, 2012).
osteosarcoma (7 papers, 2015 to 2024). A usually aggressive malignant bone-forming mesenchymal neoplasm, predominantly affecting adolescents and young adults. "Evaluated osteosarcoma cell lines showed characteristic phenotypes with unique patterns related to upregulation of MMP-7, MMP-14, BMP-7, miR-21-5p, miR-124-3p and downregulation of lncRNA MEG3." (PMID 36139691, 2022). "We found reduced expressions of MT1-MMP, MMP-2, and MMP-7 after EZH2 knockdown in osteosarcoma cells." (PMID 27223261, 2016). "Lower levels of the osteosarcoma metastasis-associated proteins CXCR4, MMP-2, MMP-7 and MMP-9 were detected in siEZH2 cells." (PMID 26265454, 2015). "MMP-2, MMP-7, MMP-9, and MMP-14 have been linked to the progression and metastasis of osteosarcoma." (PMID 38816365, 2024). "The mRNA levels for metalloproteinases, MMP-7 and MMP-14, were significantly increased in all analysed osteosarcoma cells compared to the HeLa cell line and hASCs." (PMID 36139691, 2022). "To identify the mediator of TSP‐2‐promoted osteosarcoma migration, we examined levels of MMP‐1, MMP‐2, MMP‐3, MMP‐7, MMP‐9, MMP‐12 and MMP‐13 mRNA expression following TSP‐2 stimulation." (PMID 33021341, 2020). "To identify the mediator of MCP-1-promoted osteosarcoma migration, we further examined the expression of MMP-1, MMP-2, MMP-3, MMP-7, MMP-9, MMP-12, and MMP-13 mRNA under MCP-1 stimulation." (PMID 33228783, 2020). "Studies have revealed that MMPs including MMP-1, MMP-2, MMP-3, MMP-7, MMP-9, MMP-12, and MMP-13 are significantly related to osteosarcoma metastasis and poor prognosis." (PMID 33228783, 2020). "Subsequent studies showed that the combination of thiram and HC further inhibited the proliferation and migration of osteosarcoma cells, increased apoptosis and cycle arrest, and further decreased the expression of beta-catenin, c-MYC, Cyclin-D1 and MMP7 compared with HC alone." (PMID 36978114, 2023). "Thus, in this study, we determined the expression of metalloproteinases, i.e., MMP-7 and MMP-14 involved in paediatric tumour pathogenesis, including osteosarcoma." (PMID 36139691, 2022).
Stroke (7 papers, 2017 to 2025). Sudden impairment of blood flow to a part of the brain due to occlusion or rupture of an artery to the brain. "MMP-3 and MMP-7 are also related to carotid atherosclerosis and stroke, with some polymorphisms causing variability in the risk of suffering from stroke." (PMID 37762627, 2023). "Future investigations with larger sample sizes and greater event rates are essential to clarify the predictive value of MMP-10 and MMP-7 for specific outcomes such as MI, stroke, or death." (PMID 40563493, 2025). "The AUCs for lipocalin-2, sP-selectin, glial cell-derived neurotrophic factor (GDNF), sVCAM-1, sRAGE, MMP-7, D-dimer, MMP-1, Apolipoprotein CIII, myoglobin and BNDF were ≥0.75 in predicting stroke amongst children with TBM." (PMID 33930055, 2021).
viral infection (7 papers, 2013 to 2022). "The viral infection activates NECs and causes the upregulation of MMP-7 and proinflammatory cytokines." (PMID 35435723, 2022). "High levels of matrix metalloproteinase-7 (MMP-7) have been reported as an inflammatory marker in viral infections." (PMID 36286038, 2022). "In other research, a high level of matrix metalloproteinase 7 (MMP-7) has been reported as an inflammatory marker in viral infection." (PMID 35327637, 2022). "Strikingly, more cells were infected and more MAdV-2 was produced from wild type enteroids compared to enteroids from Mmp7-/- mice, demonstrating that naturally secreted α-defensins can enhance viral infection." (PMID 28622386, 2017). "To determine if naturally secreted α-defensins impact viral infection, we compared MAdV-2.IXeGFP infection of wild type enteroids, which secrete bactericidal concentrations of α-defensins, to that of Mmp7-/- enteroids, which lack functional α-defensins." (PMID 28622386, 2017). "In this study, we compared oral MAdV-1 infection in wild type and Mmp7-/- mice and observed increased sensitivity of Mmp7-/- mice to viral disease." (PMID 26933888, 2016). "Thus, comparison of viral infection in wild type and Mmp7-/- enteroids affords an opportunity to examine the specific effects of naturally secreted α-defensins." (PMID 28622386, 2017). "MMP-7 expression following viral infection was suppressed in the LFK-administered group at DPI-7." (PMID 23853748, 2013). "Remarkably, MMP-7 levels in SAECs showed an increasing trend after viral infection, but levels of other MMPs showed no apparent difference." (PMID 35435723, 2022). "Second, MMP7 is induced in epithelial cells in response to toxic or mechanical injury, bacterial infection, or oncogenic transformation, but its expression is not affected by viral infection." (PMID 26933888, 2016).
Arthritis (6 papers, 2006 to 2025). Inflammation of a joint. "These mice were inoculated (intravenously) with an arthritogenic dose of S. aureus LS-1, and the mice deficient for MMP-7 developed significantly less-severe arthritis both clinically and histologically despite significantly increased numbers of live bacteria within the internal organs." (PMID 17129374, 2006). "In vivo, CFA induced rats’ arthritis and lung inflammation, but MMP-7 inhibitor and MMP-7 shRNA attenuated CFA-induced lung inflammation and fibrosis." (PMID 40722657, 2025). "MMP7 breaks down the extracellular matrix not only during embryonic development, reproduction, and tissue remodeling, but in disease processes such as arthritis as well." (PMID 28129359, 2017). "MMP7, a member of the matrix metalloproteinase (MMP) family, is involved in the breakdown of extracellular matrix in disease processes, such as arthritis and metastasis." (PMID 25909163, 2015). "Matrix metallopeptidase 7 is involved in the breakdown of extracellular matrix in normal physiological processes as well as in disease processes such as arthritis and metastasis." (PMID 26515461, 2016).